SOCS3 (suppressor of cytokine signaling 3)
Description:
SOCS family proteins form part of a classical negative feedback system that regulates cytokine signal transduction. SOCS3 is involved in negative regulation of cytokines that signal through the JAK/STAT pathway. Inhibits signal transduction by binding to transmembrane signaling receptors including IL6ST/gp130, LIFR, EPOR, INSR, IL12RB2, CSF3R/G-CSF-R and LEPR. Binding to JAK2 inhibits its kinase activity and regulates IL6 signaling. Suppresses fetal liver erythropoiesis. Regulates onset and maintenance of allergic responses mediated by T-helper type 2 cells (By similarity). Probable substrate recognition component of a SCF-like ECS (Elongin BC-CUL2/5-SOCS-box protein) E3 ubiquitin-protein ligase complex which mediates the ubiquitination and subsequent proteasomal degradation of target proteins. Upon OSM stimulation, negatively regulates the JAK-STAT signaling mediated through type II OSM receptor complex by interacting directly with JAK1.
Synonyms: SOCS-3; SSI-3; CIS3; SSI3; Cish3; ATOD4
Tractability: Antibody: the Human Protein Atlas places it where antibodies can reach. PROTAC: ubiquitination databases record sites on it.
Gene: Protein-coding gene on chromosome 17 (78,356,778 to 78,360,930, reverse strand). Ensembl gene ENSG00000184557.
Subcellular location (Human Protein Atlas): Cytosol; Plasma membrane
Pathways (Reactome):
Immune System: Antigen processing: Ubiquitination & Proteasome degradation; Growth hormone receptor signaling; Inactivation of CSF3 (G-CSF) signaling; Interferon alpha/beta signaling; Interferon gamma signaling; Interleukin-20 family signaling; Interleukin-4 and Interleukin-13 signaling; Interleukin-6 signaling; Regulation of IFNA/IFNB signaling; Regulation of IFNG signaling; Signaling by CSF3 (G-CSF)
Signal Transduction: PTK6 Activates STAT3; Signaling by Leptin
Gene expression (Transcription): RUNX1 regulates transcription of genes involved in differentiation of keratinocytes
Metabolism of proteins: Neddylation
Gene Ontology:
Molecular function: protein binding; protein kinase inhibitor activity; cytokine receptor binding; kinase inhibitor activity; miRNA binding; phosphotyrosine residue binding
Biological process: negative regulation of receptor signaling pathway via JAK-STAT; cell surface receptor signaling pathway via JAK-STAT; cytokine-mediated signaling pathway; interleukin-6-mediated signaling pathway; negative regulation of apoptotic process; T-helper 17 cell lineage commitment; cellular response to interleukin-17; intracellular signal transduction; protein ubiquitination
Cellular component: cytoplasmic side of plasma membrane; cytosol
Genetic constraint (gnomAD): Loss-of-function variants: 5 observed, 10.89 expected, observed/expected ratio (o/e) 0.46, 90% interval 0.24 to 0.96. The upper end of that interval is the gene's LOEUF score, 0.96, which puts it in group 4 of 6, group 1 being the genes least tolerant of losing a copy. Missense variants: 203 observed, 290.22 expected, observed/expected ratio (o/e) 0.7, 90% interval 0.62 to 0.79. Synonymous variants: 143 observed, 133.24 expected, observed/expected ratio (o/e) 1.07, 90% interval 0.94 to 1.23.
Homologues: Orthologues: chimpanzee SOCS3 (100% identical), macaque SOCS3 (100% identical), pig SOCS3 (98% identical), dog SOCS3 (98% identical), mouse Socs3 (97% identical), rat Socs3 (96% identical), guinea pig SOCS3 (96% identical), tropical clawed frog socs3 (66% identical), zebrafish socs3b (59% identical), zebrafish socs3a (56% identical), Drosophila melanogaster Socs36E (21% identical), Drosophila melanogaster Socs44A (18% identical). Paralogues in human: CISH (30% identical), SOCS2 (27% identical), SOCS1 (26% identical), SOCS6 (26% identical), SOCS7 (26% identical), SOCS4 (20% identical), SOCS5 (20% identical).
Diseases named in the same sentence as SOCS3 in open-access papers:
SOCS3 is named in the same sentence as 405 diseases in open-access papers, as found by Europe PMC text mining. Sharing a sentence is not in itself a finding about the gene and the disease. The quoted sentences say what the papers report.
Insulin resistance (204 papers, 2010 to 2025). Increased resistance towards insulin, that is, diminished effectiveness of insulin in reducing blood glucose levels. "Among them, Egr1, Lcn2 and Socs3 were more abundant in liver and closely associated with insulin resistance." (PMID 40523992, 2025). "Proteomic extracellular vesicle signatures, featuring the enrichment of adiponectin receptor fragments, phosphorylated AKT, and SOCS3, enhance diagnostic specificity by directly linking systemic insulin resistance to intra-ovarian signalling abnormalities." (PMID 41010046, 2025). "Chronic inflammation causes insulin resistance by activating SOCS3 and JNK, suppressing insulin signaling." (PMID 38397916, 2024). "IL-6 causes insulin resistance by impairing the phosphorylation of insulin receptors and receptor substrate-1, inducing the expression of SOCS-3, a potential inhibitor of insulin signaling." (PMID 39051061, 2024). "The reduced phosphorylation of JAK2 and STAT3 in LEPTIN deficient pig livers led to hepatic insulin resistance and increased fat synthesis marked by activation of SOCS3 and SREBP-1c, respectively, further confirms the value of the pig model." (PMID 37705071, 2023). "SOCS3 previously found to be important in the development of metabolic syndrome by increasing the risk of obesity and insulin resistance." (PMID 37187791, 2023). "The SOCS3 protein is the main inhibitor of leptin and insulin signaling which causes cellular leptin and insulin resistance and dampens energy production." (PMID 37207231, 2023). "This study also revealed that activation of IKKβ-NF-κB signaling by ER stress induces leptin and insulin resistance by affecting SOCS3, and these effects cause energy imbalance and weight gain." (PMID 36188456, 2022). "Remarkably, MK hindered the insulin-stimulated translocation of the glucose transporter GLUT4 to the surface of adipocytes and activated the STAT3-suppressor of cytokine signaling 3 pathway, implicated in adipocyte insulin resistance." (PMID 36204583, 2022). "The authors generated hepatocyte-specific SOCS3-deficient (L-SOCS3 cKO) mice, which unexpectedly exhibited obesity and systemic insulin resistance with age." (PMID 36078084, 2022). "It has been reported that SOCS-1 and SOCS3 are associated with insulin resistance in various cells through degradation of IRS-1 and IRS-2." (PMID 34416903, 2021). "The ability to induce insulin resistance is associated with activation of SOCS3, an inhibitor of insulin signaling in adipocytes." (PMID 33810619, 2021). "TLR4 activation triggers the upstream regulator of inflammatory pathways linked to the generation of insulin resistance, such as SOCS3, NF-κB and JNK." (PMID 32708841, 2020). "Upregulation of SOCS‐3 in the liver of diabetic mice causes insulin resistance by inhibiting tyrosine phosphorylation of IRS." (PMID 31289664, 2019). "Recently, clinical investigations have revealed that individuals with insulin resistance, or with a high risk of insulin resistance, have increased SOCS3 levels." (PMID 29973864, 2018). "In genetic analyses, SOCS3 polymorphisms and epigenetic methylation have also been associated with insulin resistance." (PMID 29973864, 2018). "Pro-inflammatory cytokines such as IL-6 and TNF-α up-regulate the expression of the suppressor of cytokine signaling 3 (SOCS3) implicated in inflammation-mediated insulin resistance in the liver and adipocytes." (PMID 30360409, 2018). "Since SOCS1 and SOCS3 have been implicated in the development of leptin and insulin resistance, we further evaluated the mRNA expression level of these genes." (PMID 29025435, 2017). "We have previously reported that β2KO mice have increased SOCS3 levels and IRTyr960 phosphorylation, which are both associated with increased TNFα levels and insulin resistance." (PMID 25138272, 2014).
Insulin resistance (continued). "Increased SOCS3 expression has been associated with insulin resistance in peripheral tissues, but it has also been shown that physical activity can lead to increased SOCS3 mRNA expression." (PMID 24997069, 2014). "HF IU increased hepatic expression of genes associated with insulin resistance (TNFα, SOCS3, PAI-1) and cellular stress (TXM, MAFF and DUSP)." (PMID 23690974, 2013). "In the recent report, hepatic SOCS3 is a mediator of insulin resistance in the liver; however, the hepatocyte-specific SOCS3-deficient mice promote systemic insulin resistance by mimicking chronic inflammation." (PMID 20351777, 2010). "Moreover, they found that SOCS1 and SOCS3 inhibit insulin signaling and cause insulin resistance by inhibiting insulin receptor substrate 1 (IRS1) and IRS2 binding to the insulin receptor in cultured L6 myotubes and 3T3L1 adipocytes." (PMID 36609306, 2023). "Moreover, SOCS3 upregulation was found to be associated with insulin resistance and hyperglycemia in patients with diabetes." (PMID 36609306, 2023). "Moreover, the Integrative Genomics Viewer (IGV) showed an enriched RARγ binding signal on the promoter regions of representative genes such as Socs3, Ptprf and Ppp2r2c, which are associated with the promotion of insulin resistance signaling." (PMID 36175396, 2022). "Indeed, SOCS3 association with inflammation, cumulative stress, and insulin resistance in obesity and diabetes is well established, and its inhibition is considered a promising strategy for the treatment of metabolic disorders in different conditions." (PMID 35631263, 2022). "Furthermore, activation of IKKβ-NF-κB signaling through ER stress in the hypothalamus is associated with dysfunction of SOCS3 signaling, which means central leptin and insulin resistance." (PMID 36188456, 2022). "Socs3 tissue-specific deficiency in liver and skeletal muscle could enhance insulin sensitivity and protect against obesity-associated insulin resistance." (PMID 31333621, 2019). "Finally, the chronic Helicobacter pylori infection is associated with an increased risk of developing T2D, as it induces hepatic insulin resistance by the c-Jun/miR-203/SOCS3 axis." (PMID 29535681, 2018). "Similarly, it was demonstrated that SOCS-3 has been implicated as a mediator of insulin resistance, and SOCS-3 protein expression was elevated in skeletal muscle of insulin resistant T2D." (PMID 28316372, 2017). "It has been reported that excessive secretion of SOCS3 may cause insulin resistance and play a role in hepatic fatty acid synthesis." (PMID 27611604, 2016). "In addition, the RBP4/retinol complex stimulates JAK2/STAT5 signaling and expression of the suppressor of cytokine signaling 3, which is implicated in insulin resistance." (PMID 25479076, 2014). "In agreement with such a possibility, heterozygous SOCS3 (SOCS3+/−) mice or mice with targeted invalidation of SOCS3 in the central nervous system (CNS) were protected against diet-induced obesity and associated insulin resistance." (PMID 23316186, 2012). "To determine whether impaired muscle insulin signaling caused by SOCS3 over-expression can be translated into systemic insulin resistance, we characterized the whole body insulin sensitivity of MCKSOCS3 mice fed a chow diet." (PMID 23115649, 2012). "However, the role of SOCS-3 as a modulator of glucose transport in the myocardium is unknown as most studies only report its upregulation in association with whole-body insulin resistance or lipid infusion." (PMID 26539824, 2015). "Therefore, high level of SOCS3 expression is closely associated with insulin resistance." (PMID 24963636, 2014). "The same cytokines induce insulin resistance systemically by inhibiting insulin receptor signalling in the liver and skeletal muscle via SOCS3." (PMID 41010046, 2025).
Insulin resistance (continued). "In hepatocytes, a rise in IL-6 bears a close association with the onset of insulin resistance, typically via the downregulation of IRS-1 tyrosine phosphorylation and SOCS-3 expressional upsurge." (PMID 40427505, 2025). "SOCS3 overexpression in the liver leads to insulin resistance and increases SREBP-1 expression, which regulates fatty acid synthesis." (PMID 40969371, 2025). "These cytokines upregulated EGR1 expression in hepatocytes, adipocytes and skeletal myocytes to transcriptionally activate its downstream targets LCN2 and SOCS3, thus aggravating insulin resistance in SH." (PMID 40523992, 2025). "SOCS3 has been demonstrated to exacerbate insulin resistance, a condition that is further intensified by sleep deprivation and metabolic dysregulation." (PMID 40024983, 2025). "Specifically, regarding genes related to insulin resistance pathway, we highlight SOCS3, GSK3B, STAT3, PTEN, TRIB3, FOXO1, and PTPRF, along with MAPK8, which plays a role in metabolic stress and inflammation." (PMID 41282288, 2025). "Overexpression of miR-16 increased IGFBP3 levels by decreasing TNF-α and SOCS3 signaling, inhibited insulin resistance, and protected retinal endothelial cells from HG-treated apoptosis." (PMID 40166052, 2025). "Research shows that IL-6 from fat tissue influences liver insulin resistance by increasing Suppressor of Cytokine Signaling 3 (SOCS3) levels." (PMID 40969371, 2025). "Studies have shown that SOCS3 is a vital risk factor for T2DM as it can inhibit insulin signaling and JAK/STAT signal channel conduction, lead to insulin resistance and higher levels of blood glucose." (PMID 39596180, 2024). "Skeletal muscle specific deletion of SOCS3 protects mice from insulin resistance induced by high-fat diet exposure, while overexpression impaired glucose homeostasis." (PMID 39100099, 2024). "These cytokines promote the recruitment and activation of Kupffer cells, which induce inflammation and hepatic insulin resistance via SOCS3." (PMID 37705071, 2023). "There is also evidence that SOCS3-mediated insulin resistance is involved in the upregulation of mediators (e.g. tumor necrosis factor-α (TNF-α), Interleukin 6 (IL6)) signaling pathways." (PMID 36609306, 2023). "We detected a positive correlation between SGLT2 and SOCS3 expression levels concomitant with the literature, as SOCS3 is a mediator of insulin resistance in the liver." (PMID 37511764, 2023). "SOCS3, as a suppressor of cytokine signaling, is considered to promote insulin resistance by inhibiting insulin and leptin signaling during the inflammatory response." (PMID 36911682, 2023). "This elevated SOCS3 expression can contribute to the development of both leptin resistance and insulin resistance within the brain and peripheral tissues." (PMID 37957462, 2023). "Over the years the members of the suppressor of cytokine signaling (SOCS) family (mainly SOCS1 and SOCS3) have received the lion’s share of the attention as key players in the development of insulin resistance." (PMID 36609306, 2023). "Wunderlich and others have shown the involvement of SOCS1 and SOCS3 in insulin resistance through the elevation of interleukin-6 (IL-6), thus leading to the activation of the JAK-STAT pathway." (PMID 37529379, 2023). "Secretion of IL-6 can elevate the expression of hepatic SOCS3, which can contribute to the development of hepatic insulin resistance." (PMID 37957462, 2023). "Over the years, the role of SOCS proteins (mainly SOCS1 and SOCS3) as negative regulators of inflammation has been recognized as crucial to the development of insulin resistance and T2D." (PMID 36078084, 2022). "IL-6-activated STAT3 can induce insulin resistance through suppressors of cytokine signaling 3 (SOCS3); it can then inhibit the PI3K-AKT pathway, which reduces protein synthesis and increases myostatin transcription." (PMID 35846289, 2022).
Insulin resistance (continued). "miR-15b was found to have a role in the inhibition of insulin resistance by decreased TNFα and SOCS3 signaling and increased IGFBP-3 levels, resulting in REC protection from hyperglycemia-induced apoptosis." (PMID 35586497, 2022). "SOCS3 can inhibit insulin secretion, and down-regulation of this gene promote insulin secretion, resulting in insulin resistance." (PMID 35606885, 2022). "Overexpression of SOCS3 in the liver induced insulin resistance in mice and SOCS3 deletion improved insulin sensitivity." (PMID 35626153, 2022). "Animal data suggest that IL-6 mediates hepatic insulin resistance via SOCS3, which blocks autophosphorylation of the insulin receptor." (PMID 34747368, 2021). "In animal models of obesity, SOCS3 mediates insulin resistance in central and in peripheral tissues." (PMID 33911072, 2021). "Increased SOCS3 due to stress and increased inflammatory cytokines is documented to inhibit AMPK, causing insulin resistance in several tissues." (PMID 33804348, 2021). "IL-6 also represents a link to insulin resistance, as it has been shown to suppress metabolic processes stimulated by insulin in hepatocytes, possibly induced by SOCS3 expression." (PMID 33810619, 2021). "IL6 is derived from many cells, including adipocytes, and serum levels of IL6 correlate with insulin resistance; however, adipose tissue-derived IL6 can regulate hepatic insulin resistance through SOCS3 upregulation." (PMID 35154608, 2021). "First, SOCS3 is an important negative regulator of the insulin signalling pathway and SOCS3 upregulation has been involved in insulin resistance." (PMID 34001206, 2021). "With regard to mRNA expression of SOCS 1 and SOCS3, almost all insulin-sensitive tissues showed a strong up-regulation in rodent models of insulin resistance, revealing a robust and direct relationship between insulin resistance and SOCS." (PMID 34574169, 2021). "By directly targeting the intracellular insulin signal transduction system, TNF-α can enhance insulin resistance through upregulating suppressor of cytokine signaling 3 (SOCS-3) and inhibiting adiponectin activity." (PMID 33505505, 2021). "SOCS3-specific knockout mice have shown improved diet-induced obesity, leptin, and insulin resistance compared with wild-type mice." (PMID 32168898, 2020). "Reduced levels of TNF-α and suppressor of cytokine signaling 3 (SOCS3) induced by miR-15b have been reported to inhibit insulin resistance in retinal endothelial cells." (PMID 32759750, 2020). "It plays a major role in the inhibition of insulin resistance via reduced TNFα and SOCS3 signaling and increased IGFBP-3 levels, resulting in REC protection from hyperglycemia-induced apoptosis." (PMID 32351607, 2020). "Insulin resistance is a common consequence of exposure to stress, where stress results in the activation of proinflammatory cytokines that will upregulate SOCS3." (PMID 32315370, 2020). "According to our previous in vivo study, administration of baicalein led to an increased level of hepatic glycogen and upregulated phosphorylation of Akt1, consequently improving the insulin resistance and decreasing the expression of SOCS3." (PMID 32019168, 2020). "SOCS3, a known modulator of insulin resistance in the liver, is a protein induced by proinflammatory cytokines that directly inhibits IRS-1/IRS-2 by binding to specific sites, inhibiting phosphorylation and targeting the receptor substrates for degradation." (PMID 32315370, 2020). "In mammals, interleukin-6 (IL6) and tumor necrosis factor have been proven to induce hepatic insulin resistance through the suppression of the cytokine signaling (SOCS3) pathway." (PMID 32754117, 2020). "It has been shown that SOCS1 and SOCS3 are involved in the induction of insulin resistance, and that the ablation of SOCS3 expression in adipose tissue of female mice improves insulin sensitivity to obesity." (PMID 33519913, 2020).